HIF1A (hypoxia inducible factor 1 subunit alpha)
Diseases named in the same sentence as HIF1A in open-access papers (continued):
Sharing a sentence is not in itself a finding about the gene and the disease.
cancer (continued). "In line with the efficiency of our system in down-regulating the hypoxia-responsive proteins including VEGF in cancer cells and its ability to reduce HIF-1α level via BRD4 depletion in zebrafish, we next evaluated the ENCTAC capacity in modulating angiogenesis, one typical hallmark of tumors." (PMID 36516252, 2022). "In cancer cells, HIF-1α may also be regulated by inducing high transcriptional and translational activity via different pathways: MAPK/ERK, JAK/STAT, and PI3K/AKT/mTOR." (PMID 36496973, 2022). "Therefore, we propose that SIRT3 activation in MPNST cells is antineoplastic at least in part by re-establishing SDH activity and counteracting HIF1α stabilization, as we have observed in xenografted cancer cells." (PMID 35393510, 2022). "The evidence so far proves that mir-210 overexpression via HIF-1α favors cancer development." (PMID 35741024, 2022). "For the development of an HIF-1α targeting cancer therapy, pathway-based regulation of HIF-1α with DNA-binding small molecules may represent an important approach." (PMID 36014432, 2022). "HIF1α also mediates a metabolic shift to a cancer-like Warburg phenomenon in PAEC." (PMID 36684555, 2022). "Hypoxia is known to upregulate expression of hypoxia-inducible factor 1α (HIF-1α), a transcription factor that can up- and down-regulate many genes involved in cancer metabolism, and enhance the expression of numerous tumor markers, co-regulate cancer cell proliferation, metastasis, and invasion." (PMID 36577992, 2022). "Furthermore, propofol has been shown to reduce both cancer cell motility and the degree of invasiveness, and lastly gives reduction of HIF-1a." (PMID 36431218, 2022). "A lack of HSF1 has been shown to dramatically deplete HIF1A and decrease angiogenesis, which is directly linked to a cancer cell’s growth and development." (PMID 36347941, 2022). "In contrast, HIF1A-regulating circRNA such as circ_EPHB4 is downregulated in cancer cells." (PMID 36230902, 2022). "Generally, in cancer cells, ROS and HIF-1α maintain a balance." (PMID 36014432, 2022). "For example, an elevated level of HIF1α in cancer cells could subsequently activate the transcription of vascular endothelial growth factor (VEGF) which promotes the formation of new blood vessels." (PMID 36319992, 2022). "Rather similar to cancer cells which adapt their metabolism to hypoxia, the HIF-1α-dependent metabolic switch to glycolysis may promote production of Th17 cells but would effectively suppress Treg generation." (PMID 36338522, 2022). "In parallel, the awareness of the importance of hypoxia and HIF-1α in cancer therapy is expanding." (PMID 35681691, 2022). "The role of HIF-1α in the apoptosis of cancer cells is controversial." (PMID 36014432, 2022). "HIF-1α is also known to be an important regulator of cancer metabolism reprograming." (PMID 35909936, 2022). "HIF-1α is a key factor for cancer cells to adapt and survive." (PMID 36010952, 2022). "Therefore, ascorbate has the potential to downregulate HIF-1α and thereby reduce the self-renewal capacity and tumorigenicity of cancer cells." (PMID 35406796, 2022). "Therefore, it is also suggested that the underlying mechanism of the pro-oxidant effect of melatonin on cancer cells involves the inhibition of HIF-1α by melatonin." (PMID 36009340, 2022). "In addition, the generated O2 can alleviate the hypoxic condition, resulting in the down-regulated expression of HIF-1α protein in cancer cells." (PMID 35277519, 2022). "The NF-κB/HIF-1α signaling pathway maintains cancer stemness and high radioresistance in CD133-positive CSCs, whereas the inhibition of this HIF-1α involving pathway reverses the EMT and reduces the radioresistance in a model with laryngeal squamous carcinoma CNE-2 stem cells." (PMID 36014432, 2022). "HIF-1α is in a complex interplay with all hallmarks of cancer." (PMID 35681691, 2022). "The constitutive expression of HIF1α and HIF2α also confers cancer cells’ resistance to apoptosis." (PMID 36079025, 2022).
cancer (continued). "However, reduction in nutrition supply in cancer cells inhibits HIF-1α activity via a mTORC1 dependent mechanism." (PMID 35327484, 2022). "Hence, we next used the UALCAN database to explore the level of HIF1α methylation in pan-cancer and its corresponding tissues." (PMID 35860430, 2022). "The data suggested that SD-induced Nrf2 and HIF-1α could be related to NPHP3 expression leading to the regulation of cancer cell death." (PMID 36498831, 2022). "Recently, many hypoxia-inhibition strategies have been used as a therapeutic approach to treat cancer through regulating/targeting of HIF-1α to overcome the cell resistance due to hypoxia in solid tumors and through suppressing the hypoxia-stimulated resistance to chemotherapies." (PMID 35399691, 2022). "miR-576-3p has been reported to regulate HIF-1α expression in cancer." (PMID 35712504, 2022). "Cancer cells increase HIF-1α protein levels in response to hypoxia to counteract cellular stress." (PMID 35202089, 2022). "Hence, pharmacological targeting of HIF-1α has been considered to be a novel cancer therapeutic strategy in recent years." (PMID 36014432, 2022). "Lactate and Pyr accumulation promote the HIF-1α stabilization in cancer cells." (PMID 35367410, 2022). "Several studies put forth other negative regulators of HIF-1α, downregulation of which may have crucial roles in gastric carcinogenesis and cancer progression such as FOXO1, melatonin, and specific miRNAs." (PMID 35681691, 2022). "In addition, a study of the correlation between carbohydrate metabolism and HIF-1α expression suggested that O-GlcNAcylation regulates glycolysis in cancer cells via HIF-1α." (PMID 36011045, 2022). "Pathways related to HIF-1α represent potential targets for cancer therapy." (PMID 36139362, 2022). "This may explain the failure of HIF-1α inhibitors since selected cancer cells will be inherently resistant to apoptosis in these circumstances." (PMID 35681691, 2022). "They analyzed hypoxic γH2AX induction in a range of cancer cell lines and demonstrated that H2AX phosphorylation is delayed in HIF-1α-deficient mouse embryo fibroblasts (MEFs) and after HIF-1α or HIF-2α knockdown in HEK293 cells, where there is a further decrease when both HIFs are knocked down." (PMID 36551689, 2022). "In addition, HIF-1α can provide sufficient nucleotides for hypoxic cancer cells by promoting anabolism, including the pentose phosphate pathway, to meet their rapid growth needs." (PMID 35350760, 2022). "In previous studies, HIF-1α was described as a mediator of apoptosis induction in cancer cells." (PMID 35626708, 2022). "Activation of receptor tyrosine kinases, such as the epidermal growth factor receptor (EGFR) and human epidermal growth factor receptor 2 (HER2), leads to increased mTOR activity and increased HIF-1α mRNA translation into protein in prostate and breast cancer, respectively." (PMID 35642641, 2022). "Furthermore, miR-138 was found to suppress the proliferation and invasion of cancer cells by inhibiting HIF1α." (PMID 36140796, 2022). "In this context, we investigate various compounds biological properties with inhibitory effects against the HIF-1 function and found that galbanic acid, clerodermic acid and corosolic acid target HIF-1α and showed potent anti-cancer properties through dysregulation of hypoxia adaptation." (PMID 35935045, 2022). "GBM cancer metabolism could also be affected by direct inhibition of the HIF-1α transcription factor." (PMID 35625738, 2022). "Several studies have shown that HIF1A was a cancer suppressor gene at Del(14q) in ccRCC." (PMID 35677048, 2022). "We previously reported on the development of NBO2 water with single-nanometer-range oxygen that could improve radiation sensitivity via the suppression of HIF-1α in an in vitro analysis of cancer cell lines." (PMID 35743281, 2022). "Both c-MYC and HIF1α act together to promote cancer cell growth and progression." (PMID 36818371, 2022).
cancer (continued). "Increased intratumor hypoxia stabilizes and activates HIF-1α, which may activate many metastatic sequences to promote local and distant site cancer recurrence." (PMID 35310917, 2022). "Furthermore, the research about the effect of hypoxia on cancer cells showed that hypoxia-inducible transcription factor α (HIF1α) affects as a transcription factor many genes involved in anaerobic metabolisms, angiogenesis, and metastasis." (PMID 36012500, 2022). "HIF1α can trigger more than thousands of genes that help in cancer metastasis." (PMID 35847841, 2022). "Taken together, the results imply that PC formation in cancer cells could be controlled by NPHP3 expression through ROS-induced HIF-1α and ERK activation under SD conditions." (PMID 36498831, 2022). "In the network diagrams in the following sections, we presented the processes/signaling molecules that commonly take part in HIF-1α signaling in diverse cancer types with pink, and processes/signaling molecules for which there is specific evidence in GC with blue." (PMID 35681691, 2022). "Thus, HIF-1α significantly enhances our molecular understanding of cancer progression and metastasis which is discussed in detail in the following sections." (PMID 35432450, 2022). "Further, HIF-1α overexpression prognosticates the poor prognosis of cancer." (PMID 35527284, 2022). "A high glucose environment increasing HIF-1α expression leads to radiotherapy resistance in cancer." (PMID 36011045, 2022). "Thus, genetic alterations and intratumoral hypoxia contribute in varying degree to the high levels of HIF-1α or HIF-2α that are observed in many human cancers." (PMID 35642641, 2022). "The mechanisms of HIF-1α have been extensively studied in multiple cancer types." (PMID 36277475, 2022). "Hypoxia drives excess supply of lipids to cancer cells, in a HIF-1a-dependent manner." (PMID 36329893, 2022). "In our proposed DMD-related lncRNA-mRNA pathway networks, PYCARD, RIPK2, and CASP1 were significantly enriched in the NOD-like receptor signaling pathway, whereas MAP2K2, LUM, RPS6, PDCD4, TWIST1, and HIF1A were significantly enriched in proteoglycans in cancers." (PMID 36619896, 2022). "We hypothesized that the stabilization of HIF-1α in BM macrophages by the clearance of apoptotic cancer cells induces the expression of key pro-inflammatory cytokines." (PMID 36496973, 2022). "The HIF-1a transcription factor is a major driver of cancer cell metabolism reprogramming." (PMID 35625738, 2022). "Furthermore, according to ECAR data, the EAAm treatment also downregulated the expression of hypoxia inducible factor 1α (HIF-1α) in M14 and HeLa, which, by upregulating glycolysis, is one of the primary regulators of the Warburg effect and cancer growth." (PMID 35367410, 2022). "In this study, suppression of NO synthesis or STAT1 activation will reduce the accumulation of HIF-1α induced by doxorubicin (DOX) in cancer cells, where DOX chemotherapy can induce HIF-1α accumulation in cells and is a condition that will limit the efficacy of DOX therapy." (PMID 35340325, 2022). "However, in addition to their shared roles in cancer onset and progression, HIF-1α and -2α also show many independent, sometimes even opposing roles in specific contexts." (PMID 36322456, 2022). "Further investigation indicated the down-regulation of HIF-1α protein expression, possibly by suppressing its synthesis, reducing the production of vascular endothelial growth factor, and inhibiting the proliferation of the cancer cells." (PMID 36558113, 2022). "Hence, targeting cancer cells’ mitochondria removes their support from HIF-1α and MAPK and enhances the antigen presentation to T cells." (PMID 36292613, 2022). "Furthermore, HIF-1α overexpression indicates the high potential of hypoxic cancer cells to develop a metastatic phenotype." (PMID 35408505, 2022). "HIF-1α can also regulate hypoxia response both in normal tissues and cancer cells." (PMID 35528614, 2022).
cancer (continued). "These pre-clinical and clinical studies decipher that PX-478 could be a potent anti-cancer agent by targeting HIF-1α in the near future." (PMID 36014432, 2022). "Therefore, the use of specific small-molecule inhibitors targeting HIF-1α is an attractive strategy for developing cancer therapeutics." (PMID 35684364, 2022). "Therefore, the poor prognosis of cancer patients results in the actual interest in studying HIF-1α as a therapeutic target in cancer disorder." (PMID 35205167, 2022). "HIF-1α plays a key role in modulating glycolysis and is involved in cancer drug resistance." (PMID 35127685, 2022). "Moreover, HIF-1α mediates cancer promotion and progression via the activation of histone deacetylases and β-catenin." (PMID 36076967, 2022). "In contrast, in cancer cells, targeting HIF-1α resulted in a cell-intrinsic inhibition of PD-L1." (PMID 35239514, 2022). "The combination routine of HIF-1α inhibitors with PDT is an efficient approach for cancer therapy." (PMID 35370727, 2022). "Furthermore, BNIP3 and NIX are target genes of HIF-1α and their upregulation stimulates mitophagy under hypoxia and inhibits cancer progression in MMTV-PyMT model under hypoxia through activated HIF." (PMID 35205167, 2022). "Hence, from this part of the review, it is evident that HIF-1α has significant role in metabolic regulation as well as survival and growth of cancer cells." (PMID 36014432, 2022). "Conversely, depletion of ADCK2 largely inhibited TNFα-induced HIF-1α stability in cancer cells." (PMID 36439873, 2022). "Indeed, the accumulation of 2-hydroxyglutarate (2-HG), an essential epigenetic regulator in cancer cells, has been documented to enhance the stabilization of HIF-1α." (PMID 35205167, 2022). "HIF-1α-dependent changes in lipid metabolism can promote the survival and growth of cancer cells." (PMID 35800058, 2022). "A dual autophagy regulatory role has been found for HIF1A in cancer." (PMID 35317831, 2022). "Stability and levels of HIF-1α in cancer cells are elevated in hypoxic environments." (PMID 35280516, 2022). "Given that CSCs typically represent a small proportion of total cancer cells and that HIF-1α is selectively activated in CSCs to maintain their properties under normoxia, we anticipated that the small number of cancer cells expressing viperin in normal conditions would be CSCs." (PMID 36227691, 2022). "These discovered cofactors can be essential to HIF1A’s regulatory functions and may lead to the discovery of new therapeutic targets in cancer treatment." (PMID 36347941, 2022). "It has been reported that HIF-1α encourages the expression of MMPs in cancer cells." (PMID 35592530, 2022). "Besides, it has been shown that activation of HIF-1α can increase resistance to various cancer therapies." (PMID 36619866, 2022). "Moreover, downregulation of HIF-1α in cancer cells was required for cetuximab-mediated autophagy as well as the sensitivity of HNSCC cells to radiation." (PMID 35158804, 2022). "The first of these mechanisms is based on the re-conversion of lactate to pyruvate, which results, among other things, in impaired HIF-1α ubiquitination and its accumulation in the cancer cells, as well as increased VEGF production, leading to an intensification of angiogenesis." (PMID 35205136, 2022). "Furthermore, hypoxia-activated HIF-1α promotes angiogenesis, autophagy, CSCs, and reprograming energy metabolism to diminish radiation damage in cancer cells." (PMID 35328212, 2022). "Hypoxia inducible factor 1 alpha (HIF1A) is a transcription factor (TF) that forms highly structural and functional protein–protein interactions with other TFs to promote gene expression in hypoxic cancer cells." (PMID 36347941, 2022). "Notably, in both cancer cells and ECs, HIF-1α accumulates earlier during hypoxia and its levels decrease more rapidly than HIF-2α during prolonged hypoxia." (PMID 36482296, 2022).
cancer (continued). "Pooled data demonstrated that high HIF-1α expression can act as a significant prognostic factor for survival outcomes and can provide a new reference point for predicting the metastasis and progression of cancer." (PMID 35845307, 2022). "Several drugs have already been designed to combat cancer by targeting HIF-1α." (PMID 36014432, 2022). "In addition, it has been demonstrated that dysregulated lncRNA levels in cancer can regulate some key regulators related to hypoxia such as HIF1A." (PMID 35846431, 2022). "CD276 has been reported to increase HIF-1α expression and promote the glycolysis of cancer cells." (PMID 35783506, 2022). "Moreover, metastasis-on-a-chip indicated that adipocyte-derived lipids induce human cancer cell migration via cancer cell HIF-1α activation." (PMID 36115986, 2022). "This compound is a promising natural inhibitor that could potentially be used to target HIF-1α-overexpressing cancer cells or combine with other endocrine therapies to reduce drug resistance or recurrence of hormone-dependent breast cancer." (PMID 36080483, 2022). "PX-478 (s-2-amino-3-[4′-N, N, -bis (chloroethyl) amino] phenyl propionic acid N-oxide dihydrochloride) is a recently developed experimental anti-cancer drug that inhibits HIF-1α expression at multiple levels including decreasing mRNA levels and inhibition of HIF-1α translation." (PMID 35805044, 2022). "Moreover, reduction in mitochondrial biogenesis to regulate oxygen consumption in cancer cell is a significant part of HIF-1α mediated metabolic alteration." (PMID 36014432, 2022). "The cancer-promoting miR-21 expression was also increased by hypoxia in a HIF-1α-dependent manner." (PMID 35053572, 2022). "HIF1A expression has been shown to be elevated in a number of human cancers." (PMID 35867798, 2022). "However, other than involvement in angiogenic progression HIF-1α also plays an important role in other hypoxia-induced hallmarks of cancer, such as induction of metastasis." (PMID 36014432, 2022). "Even though HIF-2α is structurally similar to HIF-1α, as they share a 48% identical amino acid sequence, many studies utilizing various approaches show that they have unique roles and gene targets in both normal and cancer cells." (PMID 36140753, 2022). "Furthermore, miR-186-5p can attenuate the metabolism of cancer cells by suppressing GLUT1 or HIF-1α expression." (PMID 36217480, 2022). "It has been noted before that mitochondria support HIF-1α expression and function in cancer cells." (PMID 36292613, 2022). "HIF-1α activity is also under the control of complicated regulatory networks in cancer cells." (PMID 35712504, 2022). "Studies have been reported that oxamate could induce autophagy via downregulation HIF-1α through inhibiting the Akt-mTOR signaling pathway in cancer cells." (PMID 35370938, 2022). "HIF1α plays an important role in cancer initiation, progression, and prognosis." (PMID 35860430, 2022). "Furthermore, HIF-1α can increase mitophagy and protect cancer cells from several drugs, including cisplatin, 5-FU, and GEM." (PMID 35814435, 2022). "Cancer cells can activate the transcription factor HIF-1α under hypoxic conditions." (PMID 35127685, 2022). "Thus, overcoming hypoxia/HIF-1α is a promising therapeutic strategy for hypoxia-related refractory cancer patients." (PMID 35743281, 2022). "HIF-1α inhibition is an area of active investigation in cancer therapy." (PMID 35239514, 2022). "A variety of GFs can activate HIF-1α/VEGF signaling in cancer cells." (PMID 35158804, 2022). "On the contrary, HIF-1α could induce the secretion of other cytokines, such as IL-1β by TAMs and cancer cells stimulated by hypoxia." (PMID 35565420, 2022). "In addition to the EGF and IGF systems, PDGF and basic FGF (bFGF) act as survival factors in cancer cells by engaging stimulatory signaling mechanisms mediated by HIF-1α." (PMID 35158804, 2022).